TNF (tumor necrosis factor)
Diseases named in the same sentence as TNF in open-access papers (continued):
Sharing a sentence is not in itself a finding about the gene and the disease.
Chagas disease (continued). "Conversely, our results with cytokine-treated cardiomyocytes can bring insight not only about Chagas disease, but also in other cardiac disorders where IFN-γ and TNF-α play a role, such as inflammatory cardiomyopathies of other etiology." (PMID 34867992, 2021). "Specifically, transforming growth factor β (TGF-β), tumor necrosis factor-α (TNF-α), and interferon gamma (IFN-γ) are central to the immune response and pathology of Chagas disease." (PMID 32433643, 2020). "In summary, TNF and TGF-β1 serum levels presented a weak correlation with LV systolic and diastolic functions in patients with Chagas disease." (PMID 29513876, 2018). "TNF and TGF-β1 serum levels present a weak correlation with LV systolic and diastolic function in Chagas disease patients." (PMID 29513876, 2018). "Cardiac patients exhibited higher mRNA expression of IFN-γ, TNF-α and lower mRNA expression of IL-10, Foxp3, AHR, and GATA-3 than those with the indeterminate clinical form of Chagas disease." (PMID 27115869, 2016). "In this investigation we first evaluated the production of IFN-γ, TNF-α, IL-10 and IL-17 in PBMC obtained from groups of Chagas' disease patients and in a group of benznidazol-treated individuals." (PMID 22545173, 2012). "This resulted in a low and significant TNF-α/IL-10 ratio that may have contributed to the lower mortality rate and to the higher survival time observed among coinfected animals In fact, there are several reports on the immuno-modulatory role of IL-10 in infectious diseases including Chagas disease." (PMID 20967289, 2010). "A recent study found higher levels of interferon-gamma, tumor necrosis factor-alpha, interleukin-10 and CCL3 in the myocardium of hamsters exhibiting acute symptoms of Chagas disease, when compared to asymptomatic animals." (PMID 20559542, 2010). "On the other hand, TNF-α blockade with Etanercept aggravated the progression of ventricular dysfunction in a Syrian hamster model of CCC, indicating the complexity of anti-inflammatory therapy for Chagas disease." (PMID 40297326, 2025). "We observed an inverse and statistically significant correlation between the inflammatory cytokines TNF-α, IL-6 and IFN-γ with LVEF, a worse prognosis predictor in Chagas disease, while IL-17 plasma level was positively correlated with LVEF and LVDD, indicating better heart function." (PMID 38390336, 2024). "Likewise, in the context of Chagas disease, IFN-γ acts synergistically with TNF-α through the activation of the nuclear transcription factor NF-kB for the positive regulation of iNOS expression; producing high levels of nitric oxide and RNS." (PMID 34829722, 2021). "Chagas disease is characterized by activation of cell mediated immunity (CMI), including activation of Th-1, Th-17 cells and T CD8+ lymphocytes as well as the secretion of pro-inflammatory cytokines (PICs), such as TNF-α, IFN-γ, IL-6, IL-1756–59." (PMID 33268766, 2020). "The number of TNF-producing inflammatory cells within the myocardium is higher in patients with Chagas disease and HF than in patients with the cardiac form and no HF." (PMID 29513876, 2018). "TGF-β1 and TNF serum levels and LV function - The correlation between TGF-β1 and TNF serum levels and parameters of LV systolic and diastolic function and BNP serum levels were evaluated only in the population with Chagas disease." (PMID 29513876, 2018). "Our results are in agreement with the literature because several studies using acute experimental models of infection or in humans have reported the critical role of TNF-α, IFN-γ and IL-10 in modulating the immune response in the acute phase of the Chagas disease." (PMID 23951243, 2013). "In addition to pathways in cancer and Chagas disease (American trypanosomiasis), the pathway of Xuefu Zhuyu Decoction in the treatment of CHD is also involved in the following signaling pathways: TNF signaling pathway, calcium signaling pathway, and HIF-1 signaling pathway." (PMID 33628326, 2021).
Chagas disease (continued). "It was noteworthy that Chagas disease hosts develop, upon homologous T. cruzi antigen recall in vitro, a prominent pro-inflammatory response involving IFN-γ (NK-cells and T-cells) together with TNF (monocytes, NK-cells, T-cells and B-cells) modulated by IL-10 from monocytes and B-cells." (PMID 28225764, 2017). "Another study showed that children with acute infection present higher serum levels of tumor necrosis factor (TNF)-α, sIL2R, sCD8, sCD4, and IL-6, but no change in IL-2, IL-12, and IL-8 is observed compared to healthy controls or children with asymptomatic Chagas disease in the chronic phase." (PMID 26090399, 2015). "In our cohort of chronically infected Chagas disease patients, those with detectable T. cruzi parasitemia measured through RT-PCR in peripheral blood had a higher concentration of pro-inflammatory cytokines (TNF-α, IL-1β, IL-6 and IL-17A) and IL-4 than those with negative RT-PCR." (PMID 38133693, 2023). "Two of those peptides (HSP70210-8 and HSP70316-24) recognized by CD8+ T cells of HLA-A*02:01+ Chagas disease patients from endemic areas residing in a non-endemic zone induced peptide-specific cytotoxic activity and pro-inflammatory cytokine (IFN-γ and TNF-α) secretion." (PMID 34267750, 2021).
breast tumor (124 papers, 2004 to 2025). "Biopsy samples of breast tumors show increased TNF-α expression, and this has been associated with a worse prognosis." (PMID 38201482, 2023). "This approach is particularly relevant in our study because TNFα and IL-1β were found to be expressed persistently in breast tumors, to exert powerful and causative tumor-promoting roles, and to be significantly associated with poor prognosis in patients." (PMID 33806906, 2021). "This study aims to elaborate on the association of CCL2, IL18, IL23α, and TNF-α (tumor necrosis factor-alpha) expression with the anti-proliferative effect of ECCT in rat breast tumor tissue." (PMID 32695310, 2019). "In breast tumor tissues, high expression of TNFα has been linked with ER negativity and cancer relapse." (PMID 24473087, 2014). "In previous studies looking at correlations between TP and various immune mediators in the human breast tumour microenvironment, TP expression was associated significantly with expressions of TNF-α, IL-1α, and monocyte chemoattractant protein (MCP)-1." (PMID 15150550, 2004). "An overexpression of B promotes breast tumour cell proliferation and invasion, whilst levels of FnIIIC+ variants positively correlate with disease duration and degree of joint erosion and negatively correlate with response to anti-TNF biologic therapy." (PMID 38077374, 2023). "This type of ion channel is overexpressed in breast tumors, which is associated with tumor progression and its blockade by the venom of the Buthus martensi scorpion has been shown to induce a reduction in the activation of NF-κB and TNF-α." (PMID 38137888, 2023). "It has been suggested that the scarcity of breast tumor derived cell lines has led to the apparition of several sub-lines, evidenced by different results obtained for the evaluation of related phenomena, including their susceptibility to TNF-α induced apoptosis." (PMID 16504042, 2006). "TNF-α is produced by immune cells and sometimes by tumor cells themselves in the breast tumor microenvironment." (PMID 41007766, 2025). "Our findings also suggest that the relative availability of TGF-β1 and TNF-α in the tumor niche controls the abundance of key neutrophil-recruiting chemokines, and thus regulates the degree of neutrophil recruitment to breast tumors." (PMID 40833805, 2025). "We further establish that the TGF-β1/TNF-α/p38MAPK signaling axis is a potential predictor of neutrophil recruitment in the breast tumor niche." (PMID 40833805, 2025). "The cytokines TNF‐α and IL‐2, secreted by infiltrating immune cells at the tumor site in the breast tumor‐bearing model mice, were also significantly upregulated." (PMID 41476656, 2025). "The proinflammatory signals TGF-β1 and TNF-α are upregulated in breast tumors and induce epithelial-to-mesenchymal transitions (EMT), a process linked to cancer cell aggressiveness." (PMID 40833805, 2025). "One report noted coordinated over-expression of TNF-α, IL-1β, and chemokines (CCL2, CCL5) in breast tumors, which was associated with epithelial–mesenchymal transition (EMT) and invasive behavior." (PMID 41007766, 2025). "This increase is associated with the activation of TNFα-p38-MAPK signaling axis, which finally causes breast tumor-initiating cell (BTIC) properties." (PMID 40014756, 2025). "A study conducted with triple-negative breast cancer cells MDA-MB-231 showed that TNF-α was stimulated by E5, reinforcing the activity of this oncoprotein in breast tumor cells." (PMID 38994984, 2024). "T helper 17 (Th17) cells are important inflammatory mediators in CD, and when Th17 cells reach breast tumor tissues, they upregulate a variety of cytokines including IL-17 and tumor necrosis factor-α (TNF-α)." (PMID 38406175, 2023). "In the present work, we focused our research on TNFα action in stromal cells, which are the more abundant phenotype in breast tumors." (PMID 37107188, 2023).
breast tumor (continued). "The breast tumor epithelial cells induce prostaglandin E2, tumor necrosis factor α (TNFα) and other cytokines production, which regulate the expression of aromatase." (PMID 36941680, 2023). "TNF-α is an inflammatory cytokine highly expressed in breast tumors and has been shown to induce several cellular processes, such as cell survival, cell proliferation, cell cycle, mitosis, and metastasis." (PMID 37764312, 2023). "TNFα is present in high concentrations in the breast tumor/stroma milieu and upregulates CCL2 production in 4T1 cells in vitro." (PMID 37208442, 2023). "When the colostrum macrophages were cocultured with breast tumor cells, melatonin reduced the percentage of both macrophage phenotypes and the cytokines tumor necrosis factor-alpha (TNF-α) and interleukin 8 (IL-8)." (PMID 37569777, 2023). "TNFα is consistently high in the breast tumor microenvironment, which exerts a variety of functions that affect cell malignancy and metabolism." (PMID 37107188, 2023). "Next, we experimentally verified the activation of the NF-κB pathway in the primary breast tumors, which is the major pathway activated upon TNF-α stimulation." (PMID 38201482, 2023). "Overall, these findings, together with our present study, validate that blocking TNF-α signaling can decrease breast tumor growth and have an even more marked effect in decreasing metastasis." (PMID 38201482, 2023). "When we replaced inflammation factor LPS with TNFα, Hectd3 KO also significantly inhibited lung colonization of 4T1-Luc2 breast tumor cells." (PMID 35918322, 2022). "Remarkedly, this effector mechanism is mediated by inflammatory Th2 cells releasing Th1 cytokines IFN-γ and TNF-α, which bind to receptors on breast tumor cells." (PMID 36467403, 2022). "On the other hand, the stimulation of macrophages to secrete pro-inflammatory factors such as IL-1b, IL-6, and TNF-α by exosomal transfer of miR-183 led to tumor growth and metastasis of the 4T1 breast tumor model in vivo." (PMID 36012638, 2022). "Regarding cancer, TNF-α promotes the invasion of breast tumor cells, as evidenced by in vitro experiments, up-regulating several genes associated with proliferation, invasion, and metastasis." (PMID 35269666, 2022). "TNF-α is one of the key proinflammatory cytokines that are found in breast tumor microenvironment, and it is secreted by tumor-infiltrating macrophages, stromal cells, and also by tumor cells themselves." (PMID 34572567, 2021). "Meanwhile, zinc nanoparticles loaded with porphyrin-lipid photosensitizer used for PDT in 4T1 breast tumors also reported an increase in serum TNF-α, IFNγ, and IL-2, one day after PDT." (PMID 36405502, 2021). "In view of the continuous presence of TNFα and IL-1β together in many luminal-A breast tumors, we began this study by determining the impact of TNFα + IL-1β stimulation on the morphology of stimulated MSCs." (PMID 33806906, 2021). "In the model of breast tumor mice, EA significantly reduced the level of inflammatory cytokines including IL-1β and TNF-α and increased the level of the anti-inflammatory cytokine, IL-10, in serum." (PMID 35095910, 2021). "A significantly increased expression of IL-6, IL-8, TGF-β1, and TNF-α in SC and CC isolated from primary breast tumors having a high percentage of BCSCs; further supports the significant role of inflammatory tumor environment in the expansion of CSCs." (PMID 34778599, 2021). "We tested human breast tumor epithelial cells compared to normal mammary epithelial cells by measuring the level of total and phospho-IκBα plus and minus TNFα treatment." (PMID 31909200, 2020). "For example, TNFα and/or IL-6 were strongly connected to endocrine resistance in luminal-A breast tumors, in patients as well as in model systems of cultured cells or mice." (PMID 33585241, 2020). "As seen in macrophages and HEK293 cells, knockdown of RAS clearly suppressed the levels of IL-1β and TNF-α in breast tumor cells." (PMID 32422978, 2020).
breast tumor (continued). "In animal models, both TNF-α intra-tumoral administration, in combination with different conventional therapies, and application of TNF-α monoclonal antibodies decrease tumor growth and metastatic potential of breast tumors." (PMID 32346605, 2020). "ADFs enhance release fibronectin and collagen I, increase gene expression of adipokines and adipocytokines (TNF-α, IL-6 and IL-1β) which induce invasive abilities of breast tumor cells." (PMID 31398937, 2019). "In our study, we have used potent and most clinically relevant pro-inflammatory cytokines - TNFα and IL-1β - that are expressed in breast tumors and have pro-metastatic functions in TNBC." (PMID 31031757, 2019). "In this context, the authors also observed TNFα overexpression and activation of the TNFα-p38-MAPk signaling axis, which contributed to the acquisition of breast tumor-initiating cell characteristics." (PMID 30939818, 2019). "In co-culture condition, although both IL-6 and TNF-α mRNA level in adipocytes were significantly upregulated in the presence of breast tumor cells, the level of TNF-α was undetectable in the supernatant of adipocytes with or without breast tumor cells." (PMID 30013512, 2018). "Driven by interleukin (IL)-4 and IL-10, tumor necrosis factor-alpha (TNFα), macrophage colony-stimulating factor (M-CSF), or hypoxia, breast tumor microenvironment facilitate M1 differentiation into M2." (PMID 30134816, 2018). "In this study, we showed that SNAIL1 regulates expression of cytokines in primary breast tumor cells including IL-1α, IL-6, TNFα, and GM-CSF." (PMID 29593211, 2018). "Secretion of multiple cytokines including IL-6, IL-12, IL-1β and TNF-α from DCs was measured by ELISA Kit after transwell co-culture (diffusion model) or direct co-culture of immature DCs with the ablated breast tumor cells (cell contacting model) for 24 h." (PMID 30583459, 2018). "TNFα acts on breast tumor TNF receptors evoking the release of chemotactic proteins (e.g. MCP-1/CCL2)." (PMID 28441391, 2017). "Studies with MSCs activated by TNFα + TGFβ1 revealed that they release factors that can affect other cells in their microenvironment and induce breast tumor cell elongation, migration, and scattering out of spheroid tumor masses." (PMID 28553282, 2017). "Investigations strongly suggest that the expression of TNF-α in breast tumours actually promotes tumour growth." (PMID 28479926, 2017). "Along these lines, in recent preliminary studies, we have generated mRNA expression profiles of breast tumor cells grown in the presence of CM derived from TNFα + TGFβ1-stimulated MSCs." (PMID 28553282, 2017). "Of note, as a consequence of the joint activities of TNFα + TGFβ1 stimulation, the MSCs released factors that have led to elevated migratory and scattering processes in breast tumor cells." (PMID 28553282, 2017). "TNFα is present in high concentrations throughout the breast tumor/ stroma milieu, and upon activation of TNFα receptors, can trigger a powerful perpetual cascade of NF-κB activation." (PMID 28441391, 2017). "Previous studies have found increased concentrations of TNF-α in the breast tumor cytosol, and, presence of TNF-α has been strongly correlated with metastatic, invasive breast tumor phenotype." (PMID 29088874, 2017). "To this end, we determined the effects of factors that were secreted by MSCs—following their activation by TNFα + TGFβ1 together—on characteristics of breast tumor cells that are connected to increased motility and spreading." (PMID 28553282, 2017). "Quantitative real-time PCR (qRT-PCR) analysis revealed that the mRNA levels of TNF-α were higher in 24 cases of clinical breast tumor tissues relative to their adjacent peritumor tissues (*p<0.05, Wilcoxon's signed-rank test)." (PMID 28938560, 2017). "A cascade-type of interaction was found in adipose tissue-derived MSCs, which upon priming with TNFα released TGFβ1 that, in turn, elevated the malignancy phenotype of breast tumor cells." (PMID 28553282, 2017).